SCARNA10 (small Cajal body-specific RNA 10)
Synonyms: U85; lnc; MBI; 52
Gene: Small nucleolar RNA gene on chromosome 12 (6,510,222 to 6,510,551, forward strand). Ensembl gene ENSG00000239002.
Gene Ontology:
Biological process: RNA processing
Cellular component: Cajal body; nucleolus
Homologues: Orthologues: chimpanzee SCARNA10 (99% identical), macaque SCARNA10 (98% identical), pig SCARNA10 (87% identical), rabbit SCARNA10 (86% identical), mouse Scarna10 (82% identical), guinea pig SCARNA10 (82% identical), rat Scarna10 (80% identical).
Diseases named in the same sentence as SCARNA10 in open-access papers:
SCARNA10 is named in the same sentence as 7 diseases in open-access papers, as found by Europe PMC text mining. Sharing a sentence is not in itself a finding about the gene and the disease. The quoted sentences say what the papers report.
Hepatic fibrosis (1 paper, 2022). The presence of excessive fibrous connective tissue in the liver. "Previously, we identified lncRNA Small Cajal body-specific RNA 10 (SCARNA10) is up-regulated in the serum and liver tissue samples from patients with advanced hepatic fibrosis, which promotes liver fibrosis both in vitro and in vivo through inducing HCs apoptosis and HSCs activation." (PMID 35443674, 2022).
ischemic stroke (1 paper, 2019). A stroke disorder caused by obstruction of blood flow to the brain, due to thrombotic (local blood clot formation) or embolic (due to a blood clot or other material traveling from another site) event. "Based on the qPCR results, three LncRNAs (SCARNA10, TERC, LINC01481) exhibited higher expression (p < 0.01), and three LncRNAs (FLJ23867, H3F3AP6, TNPO1P1) exhibited lower expression (p < 0.05) in ischemic stroke patient PBMCs than in healthy control PBMCs." (PMID 30774621, 2019).
SCARNA10 also shares sentences with these, for which no sentence is quoted: congenital heart block (1 paper); lupus (1); ovarian carcinoma (1); Sepsis (1); tumor (1).